USP29 (ubiquitin specific peptidase 29)
Description:
Deubiquitinase involved in innate antiviral immunity by mediating 'Lys-48'-linked deubiquitination of CGAS, thereby promoting its stabilization.
Synonyms: HOM-TES-84/86
Tractability: Antibody: the Human Protein Atlas places it where antibodies can reach. PROTAC: its protein half-life has been measured.
Gene: Protein-coding gene on chromosome 19 (57,119,138 to 57,131,926, forward strand). Ensembl gene ENSG00000131864.
Subcellular location: Cytoplasm, perinuclear region
Subcellular location (Human Protein Atlas): Plasma membrane; Cytosol
Gene Ontology:
Molecular function: protein binding; cysteine-type deubiquitinase activity; cysteine-type endopeptidase activity
Biological process: defense response to virus; G1/S transition of mitotic cell cycle; positive regulation of type I interferon-mediated signaling pathway; protein K48-linked deubiquitination; protein stabilization; protein deubiquitination
Cellular component: plasma membrane; perinuclear region of cytoplasm
Genetic constraint (gnomAD): Loss-of-function variants: 1 observed, 0.48 expected, observed/expected ratio (o/e) 2.09. That is too few expected variants to judge how well the gene tolerates losing a copy. Missense variants: 1,100 observed, 1,126.5 expected, observed/expected ratio (o/e) 0.98, 90% interval 0.93 to 1.03. Synonymous variants: 386 observed, 410.94 expected, observed/expected ratio (o/e) 0.94, 90% interval 0.86 to 1.02.
Homologues: Orthologues: macaque USP29 (91% identical), dog USP26 (49% identical), mouse Usp29 (41% identical), rat Usp29 (40% identical), guinea pig Usp26 (36% identical). Paralogues in human: USP26 (46% identical), USP37 (46% identical), USP32 (14% identical), USP24 (12% identical), USP19 (12% identical), USP8 (12% identical), USP3 (12% identical), USP9X (12% identical), USP9Y (12% identical), USP43 (12% identical), USP31 (12% identical), USP38 (12% identical), and 59 more.
Diseases named in the same sentence as USP29 in open-access papers:
USP29 is named in the same sentence as 31 diseases in open-access papers, as found by Europe PMC text mining. Sharing a sentence is not in itself a finding about the gene and the disease. The quoted sentences say what the papers report.
hepatocellular carcinoma (6 papers, 2021 to 2024). A malignant tumor that arises from hepatocytes. "Previous studies have indicated the oncogenic role of USP29 in several cancer types, including the non-small cell lung cancer, colorectal cancer, hepatocellular carcinoma and triple-negative breast cancer." (PMID 38233848, 2024). "Consistently, USP29 was also reported to stabilize HIF1α in hepatocellular carcinoma by another group." (PMID 38233848, 2024). "Besides, USP29 overexpression augments stemness of lung cancer cells after chemotherapy while USP29 knockdown reduces aerobic glycolysis and attenuates Sorafenib resistance in hepatocellular carcinoma cells." (PMID 36373629, 2023). "Studies have shown that USP29 is related to HIF-1α in hepatoma cells." (PMID 35875077, 2022). "USP29 cooperates with phosphatase SCP1 to stabilize Snail protein, thereby promoting gastric cancer cell migration and mediating HIFα stabilization to induce sorafenib resistance in hepatocellular carcinoma cells by upregulating glycolysis." (PMID 35638730, 2022).
gastric cancer (5 papers, 2022 to 2024). A primary or metastatic malignant neoplasm involving the stomach. "In this study, we found that USP29 expression was significantly upregulated in gastric cancers and associated with poor patient survival." (PMID 38233848, 2024). "Our findings demonstrated that USP29 was an important driver of gastric cancer in vivo, and uncovered a key molecular mechanism underlying gastric cancer progression." (PMID 38233848, 2024). "Here we observed that USP29 was overexpressed in gastric cancers and associated with poor patient outcomes." (PMID 38233848, 2024). "We next dissected the mechanisms underlying the upregulation of USP29 in gastric cancers." (PMID 38233848, 2024). "We next revealed that overexpression of USP29 in gastric cancer cell lines MGC-803 and SNU-216 significantly promoted the tumor cell proliferation." (PMID 38233848, 2024). "To understand the potential role of USP29 in gastric cancer, we first analyzed the USP29 mRNA expression in normal and gastric cancers using the RNA-seq database, and revealed that USP29 is markedly overexpressed in the tumor tissues." (PMID 38233848, 2024). "We found that USP29 stabilizes AURKB in gastric cancer, neuroblastoma, lung cancer and colorectal cancer." (PMID 38233848, 2024). "In this study, we revealed that USP29 was overexpressed in gastric cancers and promoted tumor cell proliferation." (PMID 38233848, 2024). "The expression of USP29 in normal and gastric cancer tissues was analyzed by bioinformatics analysis, immunohistochemistry and immunoblot." (PMID 38233848, 2024). "Through a mass spectrometry analysis of USP29 binding proteins, we identified USP29 as a novel AURKB deubiquitinase, which specifically deconjugates its K48-linked polyubiquitination and is crucial to AURKB stabilization in gastric cancer cells." (PMID 38233848, 2024). "We also investigated the molecular mechanism and identified a novel FUBP1-USP29-AURKB regulatory axis that enables the oncogenic role of USP29 in gastric cancer." (PMID 38233848, 2024). "This study revealed an underlying molecular mechanism involving the oncogenic role of USP29, and identified a potential therapeutic target for gastric cancer." (PMID 38233848, 2024). "More importantly, deletion of Usp29 in mice significantly suppressed the carcinogenesis in the BaP-induced gastric cancer model." (PMID 38233848, 2024). "While USP29 was reported to promote gastric cancer cell migration in vitro, the exact role of USP29 in regulating gastric carcinogenesis remains unknown." (PMID 38233848, 2024). "The results confirmed the overexpression of USP29 in human gastric cancer tissues." (PMID 38233848, 2024). "Our findings may provide rationales for development of therapeutic strategies for gastric cancers by targeting USP29." (PMID 38233848, 2024). "Considering the important role of AURKB in controlling cell cycle, we reasoned that USP29 may promote gastric cancer cell proliferation by regulating cell cycle progression." (PMID 38233848, 2024). "To test this hypothesis, we ectopically expressed Flag-USP29 in gastric cancer cells and revealed that USP29 overexpression increased the AURKB protein levels." (PMID 38233848, 2024). "The potential role of USP29 in gastric cancer remains largely unknown, while USP29 was reported to stabilize Snail1 and promote the migration of gastric cancer cells in vitro." (PMID 38233848, 2024). "Importantly, there was a significant correlation between FUBP1 and USP29 protein expression levels (R = 0.5074, p = 0.0019) in 35 gastric cancer samples, suggesting that FUBP1 may regulate USP29 expression in vivo." (PMID 38233848, 2024). "Here, we first depleted FUBP1 expression in gastric cancer cell lines using shRNAs and demonstrated that knockdown of FUBP1 markedly suppressed the gene expression of USP29 in all three cell lines." (PMID 38233848, 2024). "However, whether FUBP1 is a bona fide regulator of USP29 in gastric cancers remains unclear." (PMID 38233848, 2024).
gastric cancer (continued). "Activation of USP29 by FUBP1 promotes the stability of AURKB and its oncogenic functions in gastric cancer." (PMID 39605891, 2024). "In terms of mechanism, USP29 is transcriptionally activated by FUBP1, and the deregulated USP29 interacts with and stabilizes AURKB, forming a FUBP1-USP29-AURKB axis that enables tumor cell proliferation and survival in gastric cancers." (PMID 38233848, 2024). "USP29 blocks Snail degradation and accelerates epithelial-mesenchymal transition (EMT) and cell migration in gastric cancer." (PMID 36373629, 2023). "Moreover, co-immunoprecipitation (Co-IP) using MGC-803 and HGC-27 cell lysates validated the specific interaction between endogenous USP29 and AURKB in gastric cancer cells." (PMID 38233848, 2024). "We then detected the USP29 protein level in gastric cancer tissue chip (including 5 normal gastric tissues and 35 tumors) using IHC." (PMID 38233848, 2024).
lung carcinoma (5 papers, 2020 to 2024). "Elevated USP29 expression associated with enhanced cancer stem cell properties in lung adenoma cells and poor prognosis in lung cancer." (PMID 32968046, 2020). "In addition, USP29 overexpression induced by chemotherapy and oxidative stress treatment can promote chemotherapy resistance by hijacking the USP29/Snail1 axis, which is associated with enhanced cancer stem cell properties, poor prognosis and drug resistance in lung cancer." (PMID 36969062, 2023). "Further analyses identifying different histological subtypes of lung cancer by discriminating between lung adenocarcinoma (n = 720) and squamous cell carcinoma (n = 524) revealed USP29 expression as a significant prognosis indicator in adenocarcinoma rather than squamous cell carcinoma." (PMID 32968046, 2020). "It consists of three members, USP26, USP29 and USP37, of which USP26 is a positive regulator of Androgen Receptor in prostate cancer cells, USP37 directly deubiquitinates and stabilizes c-Myc in lung cancer, and USP29 has been recognized as a regulator of the checkpoint adaptor Claspin." (PMID 34272356, 2021). "As deregulation of AURKB is observed in different tumors, to test whether USP29 is a global regulator of AURKB, we analyzed AURKB protein expression in neuroblastoma SKN-BE2, lung cancer A549 and colorectal cancer HCT116 cells with or without USP29 depletion." (PMID 38233848, 2024).
colorectal cancer (4 papers, 2023 to 2024). A primary or metastatic malignant neoplasm that affects the colon or rectum. "Indeed, our findings, along with previous reports that depletion of USP29 caused cell cycle arrest and apoptosis in cervical cancer, colorectal cancer, and osteosarcoma cell." (PMID 38233848, 2024). "USP29 (ubiquitin-specific peptidases 29) deubiquitinates the KIAA1429 protein to prevent ubiquitin-mediated proteasome degradation in colorectal cancer." (PMID 39456252, 2024). "Similarly, USP29 upregulation mediates KIAA1429 deubiquitination, thereby stabilizing SOX8 mRNA and protein levels through m6A modification to facilitate malignant proliferation in colorectal carcinoma (CRC)." (PMID 37391814, 2023).
breast carcinoma (3 papers, 2022 to 2025). "In line with in vitro results, the depletion of USP29 significantly decreased the frequency of breast cancer stem cells." (PMID 36782089, 2023). "The stable overexpression of USP29 in luminal breast cancer cell MCF‐7 decreased the level of epithelial marker E‐cadherin and increased the expression of mesenchymal marker Vimentin, whereas the 3A mutant failed to induce such phenotypes." (PMID 36782089, 2023). "We first overexpressed USP29 in luminal breast cancer cell MCF‐7, in which the expression of USP29 and TWIST1 is much lower than TNBC cells." (PMID 36782089, 2023). "First, USP29 and TWIST1 protein levels were examined in several luminal and basal like breast cancer cell lines." (PMID 36782089, 2023). "Protein levels of USP29 and TWIST1 were much higher in basal like breast cancer cell lines." (PMID 36782089, 2023).
neuroblastoma (3 papers, 2024). Neuroblastoma (NB) is the most common solid, extracranial childhood tumor. "USP29 has also been shown to promote neuroblastoma progression by upregulating glycolysis and glutamine catabolism." (PMID 38725484, 2024). "Knockout of Usp29 significantly prolongs the survival of tumor-bearing mice by reducing the expressions of MYC and HIF1α in neuroblastoma and B-cell lymphoma." (PMID 39664521, 2024). "The study has shown that CRISPR-mediated depletion of ubiquitin-specific peptidase 29 (USP29) leads to the disruption of intermediates accountable for involvement in glycolysis and nucleotide biosynthesis in neuroblastoma cell lines." (PMID 38725484, 2024). "We previously reported that USP29 stabilizes oncogenic MYC (including c-MYC and N-MYC) and HIF1α in normoxia and hypoxia, respectively, thereby promoting tumor metabolism and progression in c-MYC driven B cell lymphoma and N-MYC driven neuroblastoma." (PMID 38233848, 2024).
lung adenocarcinoma (2 papers, 2020 to 2022). A carcinoma that arises from the lung and is characterized by the presence of malignant glandular epithelial cells. "As a whole, our collective findings from both in vitro and in vivo investigations suggest that USP29 upregulation appears to be efficient in enhancing cancer stem cell-associated characteristics in lung adenocarcinoma cells." (PMID 32968046, 2020). "Previous research proved that USP29 upregulation enhances the cancer stem cell-like characteristics in lung adenocarcinoma cells to promote tumorigenesis in athymic nude mice." (PMID 35281055, 2022). "Taken together, our findings unravel an oxidative stress-induced USP29-Snail1 regulatory pathway integrated by lung adenocarcinoma cells in response to chemotherapies to acquire cancer stem cell-like characteristics and develop drug resistance." (PMID 32968046, 2020). "Bioinformatic analysis revealed a reverse correlation between USP29 expression and patient prognoses in lung adenocarcinoma." (PMID 32968046, 2020). "Our findings uncover a novel mechanism by which chemotherapy induces cancer stemness and suggest USP29 as a potential therapeutic target to impede the development of chemoresistance and metastasis in lung adenocarcinoma." (PMID 32968046, 2020). "USP29 upregulation enhances the cancer stem cell-like characteristics in lung adenocarcinoma cells to promote tumorigenesis in athymic nude mice." (PMID 32968046, 2020). "Bioinformatic analysis reveals a reverse correlation between USP29 expression and prognosis in lung adenocarcinoma patients." (PMID 32968046, 2020). "Indeed, in our endeavors to knock down USP29 expression in lung adenocarcinoma cell lines, the efficiency remained unsatisfactory with numerous attempts using siRNAs and shRNAs." (PMID 32968046, 2020). "Therefore, we next sought to investigate the influence of cellular oxidative stresses on USP29 expression in lung adenocarcinoma A549 and H1299 cells." (PMID 32968046, 2020). "To evaluate the competence of USP29 in provoking lung adenocarcinoma cells into acquiring mesenchymal features and enhancing cell stemness, we conducted phenotypic assays to examine the spheroid formation and migration of H1299 and H1975 cells stably overexpressing USP29." (PMID 32968046, 2020). "Such tumor-promoting effects of USP29 were experimentally validated through a series of in vitro and in vivo phenotypic assays, with several lines of evidence in support of the notion that USP29 expression positively correlated with the enhanced stemness of lung adenocarcinoma cells." (PMID 32968046, 2020).
Parkinson disease (2 papers, 2019 to 2021). A progressive degenerative disorder of the central nervous system characterized by loss of dopamine producing neurons in the substantia nigra and the presence of Lewy bodies in the substantia nigra and locus coeruleus. "Recently, USP29 was found to be abundantly expressed in the brain and contributed to the progression of Parkinson's disease." (PMID 34824671, 2021).
viral infection (2 papers, 2021 to 2022). "To examine whether USP29-mediated stabilization of ORF9b affects viral infection, we first examined the effect of USP29 on VSV-eGFP replication in the presence of ORF9b." (PMID 35638730, 2022). "However, the direct regulation of USP29 on viral proteins or viral infections has not yet been reported." (PMID 35638730, 2022).
adenovirus infection (1 paper, 2023). "To investigate the effect of USP29 on hepatocyte apoptosis and inflammatory response in response to H/R stimulation in vitro, we overexpressed USP29 in primary hepatocytes by adenovirus infection and obtained USP29 knockout primary hepatocytes by isolating the livers of USP29-KO mice." (PMID 37304282, 2023).
Burkitt lymphoma (1 paper, 2024). A rare form of malignant mature B-cell non-Hodgkin lymphoma. "Through re-analysis of the RNA seq data using SKN-BE2 and Burkitt’s lymphoma Ramos cells with or without USP29 depletion (GSE180797), we revealed that USP29 depletion resulted in significant downregulation of AURKB pathway." (PMID 38233848, 2024).
cholangiocarcinoma (1 paper, 2021). A carcinoma that arises from the intrahepatic biliary tree (intrahepatic cholangiocarcinoma) or from the junction, or adjacent to the junction, of the right and left hepatic ducts (hilar cholangiocarcinoma). "The top-ranked somatic eQTL genes with missense mutations include USP29 in cholangiocarcinoma (CHOL) and AMELX, CNTN5, and OR1L3 in lymphoid neoplasm diffuse large B-cell lymphoma (DLBC)." (PMID 33691015, 2021).
colon cancer (1 paper, 2021). "To investigate the expression of USP29 in human colon cancer tissues, we performed an immunostaining analysis in a tissue microarray (TMA) containing colon cancer tissues (n = 32) and corresponding normal tissues (n = 32) obtained from the ISU Abxis TMA." (PMID 34072621, 2021). "We found that USP29 was highly upregulated in colon cancer tissue when compared to its corresponding normal tissue." (PMID 34072621, 2021). "In this research, we observed that the rate of USP29 overexpression was higher in colon cancer patient tissues relative to its corresponding normal tissues." (PMID 34072621, 2021). "Altogether, our results show that USP29 is highly upregulated in colon cancers and promotes tumorigenesis in vitro and in vivo." (PMID 34072621, 2021). "Because USP29 facilitates colon cancer proliferation, we wondered whether USP29-depleted HCT116 cells might inhibit colon cancer growth in vitro and in vivo." (PMID 34072621, 2021). "In conclusion, our study shows that elevated expression of USP29 promotes malignancy in CRC, suggesting that USP29 could be a promising target for colon cancer therapy." (PMID 34072621, 2021). "Altogether, these data indicate that USP29 is a novel DUB that promotes tumorigenesis in CRC, making it a promising therapeutic target for colon cancer." (PMID 34072621, 2021). "Given that USP29 promotes the proliferative behavior of colon cancer cells, we examined its role in the canonical DNA damage and cell-cycle progression of HCT116 cells by generating USP29 knockout using the CRISPR-Cas9 system." (PMID 34072621, 2021). "Our results showed that USP29 and Ki67 are not binding each other, suggesting that the expression of USP29 increases Ki67 expression in colon cancer cells without interacting with Ki67." (PMID 34072621, 2021).
COVID-19 (1 paper, 2022). A disease caused by infection with severe acute respiratory syndrome coronavirus 2. "To verify whether USP29 is an effective target for SARS-CoV-2 therapy, we examined the possible correlation between ORF9b expression and COVID-19 disease progression." (PMID 35638730, 2022).
ischemia (1 paper, 2023). A hypoperfusion of the BLOOD through an organ or tissue caused by a PATHOLOGIC CONSTRICTION or obstruction of its BLOOD VESSELS, or an absence of BLOOD CIRCULATION. "To obtain the optimal conditions, we examined the USP29 expression changes at the protein level after 1 h of ischemia and 3, 6, and 24 h of reperfusion." (PMID 37304282, 2023).
ischemic stroke (1 paper, 2021). A stroke disorder caused by obstruction of blood flow to the brain, due to thrombotic (local blood clot formation) or embolic (due to a blood clot or other material traveling from another site) event. "In summary, we prove that USP29 upregulation during cerebral I/R injury is essential for oxidative damage and neuronal apoptosis of the brain through regulating SIRT1 and that targeting USP29 may be helpful for designing effective therapeutic strategies for ischemic stroke." (PMID 34824671, 2021).